IL1B (interleukin 1 beta)
Diseases named in the same sentence as IL1B in open-access papers (continued):
Sharing a sentence is not in itself a finding about the gene and the disease.
diabetes (continued). "PATs from SENP1-aP2KO mice expressed high levels of IL-6, TNF-α and IL-1β at the age of 7 weeks before the onset of diabetes, and these proinflammatory cytokines were higher in the PATs compared with other adipose depots." (PMID 26596471, 2015). "Based on our data, comparison of microglia, neurons, IL-1β, and VEGF levels in diabetic WT and KO mice suggests that diabetes has pronounced and detrimental effects on retinal integrity and induces microglial reactivity and IL-1β release." (PMID 26514658, 2015). "As a therapeutic in diabetes, reduction of IL-1β, either by soluble receptor antagonism or antibody sequestration and neutralization was not effective in human clinical trials." (PMID 26555476, 2015). "Diabetes as the sole explanation is however contradicted by the IL-1RA/IL-1β ratio being significantly higher in Charcot patients due to lower IL-1β being lower than in diabetic controls." (PMID 26692902, 2015). "We found that pioglitazone and resveratrol significantly suppressed liver TNF-α and IL-1β levels in Balb/C mice with MG-induced diabetes." (PMID 25884658, 2015). "EMCV-induced diabetes in mice is attenuated by daily injection of neutralizing antibodies against the cytokines interleukin-1 (IL-1β) or tumor necrosis factor (TNF-α), or administration of aminoguanidine, a selective iNOS inhibitor." (PMID 26295266, 2015). "In non-pregnant tissues, endoplasmic (ER) stress is increased in diabetes and can induce IL-1β via inflammasome activation." (PMID 25849717, 2015). "The role of inflammatory cytokines TNF-α and IL-1β in the damage of retinal endothelial cells during the early and late stages of diabetic retinopathy in a rat model with streptozotocin-induced diabetes has been investigated." (PMID 26262605, 2015). "There is a significant elevation in the interleukin-6 (IL-6), C-reactive protein (CRP), tumour necrosis factor-alpha (TNF-α) and IL-1β levels in preclinical diabetes samples." (PMID 26596471, 2015). "Müller cells have been reported to produce increased amount of IL-1β when exposed to high glucose in vitro, in which caspase-1/IL-1β signaling plays an important role in diabetes-induced retinal pathology." (PMID 26245868, 2015). "A number of approaches have aimed to neutralize IL-1β in a bid to assess the therapeutic effectiveness in human diabetes." (PMID 26555476, 2015). "Our study also indicated that the treatment of chelerythrine downregulated CD36 and IL-1β as well as inflammation related genes like IFNγ and TNFα, which are of great benefits for the treatment of diabetes." (PMID 26183621, 2015). "The notion of an IL-1β hysteresis is supported by data from different studies, which showed the effectiveness of glucose control in pre-diabetes or newly diagnosed patients and the ineffectiveness of glucose control in long-standing T2D patients." (PMID 25167060, 2014). "Diabetes is considered as a kind of inflammatory and metabolic diseases, so the overproduction of IL-6, TNF-α, and IL-1β has been observed in people with diabetes." (PMID 24995360, 2014). "Cytokines such as IL-6, IL-1β, and TNF-α are known for their involvement in the process of bone loss in diabetes." (PMID 24803925, 2014). "Inflammation has been associated with the development of insulin resistance, beta cell apoptosis and evolution of diabetes, and IL-1β is one of the main inflammatory cytokines in the process." (PMID 24650557, 2014). "Remarkably, some authors have reported that treatment with soluble IL-1 receptor or neutralizing anti-IL-1β pAb prevents cyclophosphamide-induced diabetes in NOD mice." (PMID 24968718, 2014). "When compared with the control rats, diabetic rats showed elevated mRNA and protein levels of NLRP3, ASC, caspase-1 and IL-1β beginning at 4 or 8 weeks of diabetes (all p<0.01)." (PMID 25136835, 2014).
diabetes (continued). "The NLRP3 inflammasome has been implicated in the pathogenesis of various disorders like asbestosis, silicosis, gout, Alzheimer’s disease and diabetes, mostly through the production of IL-1β." (PMID 24915862, 2014). "It seems that beneficial effect of Achillea millefolium L. on STZ- induced diabetes is at least partly due to amelioration of IL-1β and iNOS gene over expression which can have a β-cell protective effect." (PMID 25635252, 2014). "Consistent with previous studies, we found an increased expression of IL-1β in the left ventricle of diabetes rats." (PMID 25136835, 2014). "In humans, though absent in fresh PMBCs, iNKT17 cells are detected in vitro with a higher frequency in T1D patients compared to control subjects in the presence of the proinflammatory cytokine IL-1β, known to contribute to diabetes occurrence." (PMID 24788601, 2014). "Our results clearly indicate that diabetes leads to increased IL-1β and TNF-α immunoreactivity in the kidney." (PMID 24817793, 2014). "In conclusion it seems that beneficial effect of Achillea millefolium L. on STZ-induced diabetes is at least partly due to amelioration of IL-1β and iNOS gene over expression which can have a β-cell protective effect." (PMID 25635252, 2014). "Consistent with this, diabetes-induced increase in the levels of inflammatory cytokine IL-1β, was also ameliorated by the nutrients." (PMID 24479616, 2014). "This large pooled analysis included more than 1000 patients with type 2 diabetes mellitus (mean duration: ~5 years) treated for up to 1.4 years either with canakinumab, an IL-1β blocker or placebo." (PMID 24884602, 2014). "Recent clinical studies suggest sustained treatment effects of interleukin-1β (IL-1β)–blocking therapies in type 2 diabetes mellitus." (PMID 24918743, 2014). "We found that patients who had sulphonylurea in their treatment regimen for diabetes had a significantly weaker IL-1β response (p = 0.04) as compared to patients who were on non-sulphonylurea containing regimens." (PMID 24762472, 2014). "Deletion of MyD88 from only marrow-derived cells totally inhibited the endothelial ICAM-1 induction in retinas from diabetic animals, and signaling through both TLR2/4 and IL-1β contributed partially to altered regulation of ICAM-1 in diabetes." (PMID 23874797, 2013). "In this study, mRNA levels of IL-1β, IL-6 and ICAM-1 were increased in the retinas of type 2 diabetic rats after 2 months of diabetes supporting the notion that chronic inflammation underlies the vascular pathology in type 2 diabetes." (PMID 23383097, 2013). "TXNIP has been shown to modulate inflammation and oxidative stress in β-cells, including IL-1β which is known to be a key mediator of islet dysfunction and destruction in diabetes." (PMID 23691179, 2013). "In contrast, the proinflammatory background of diabetes, which includes increased placental levels of TNFα, IFNγ, and IL-1β, promotes enhanced CX3CL1 gene expression." (PMID 23956503, 2013). "The renal expression of inflammatory cytokines such as TNF-α and IL-1β was demonstrated to increase in diabetes, contributing to the development of DN." (PMID 24027593, 2013). "The renal expression of inflammatory cytokines such as TNF-α, IL-6 and IL-1β were demonstrated to increase in diabetes, contributing to the development of DN." (PMID 24499158, 2013). "Our data indicate that elevations in IL-1β and IL-12 at the initial stages of KRV+pIC treatment, coupled with sustained elevations of haptoglobin, are associated with progression to diabetes in BBDR rats." (PMID 24147110, 2013). "Activated MC/MPs express inflammatory cytokines such as CCL2, TNFα, and IL-1β in experimental diabetes." (PMID 24278148, 2013). "We discovered for the first time that IL-1β expression was reduced in sensory neurons and peripheral nerve in diabetes." (PMID 24152426, 2013). "Our finding of increased IL-1β expression in rat retinal vessels in diabetes indicates that retinal vascular cells are a source of IL-1β in vivo." (PMID 22615852, 2012).
diabetes (continued). "The finding that of the different cell types tested only retinal microvascular endothelial cells upregulated IL-1β when cultured in HG pointed to the retinal vascular endothelium as a primary source of IL-1β in diabetes." (PMID 22615852, 2012). "In the rat retina, IL-1β expression began to increase between 1.5 and 2.5 months after the onset of diabetes and continued to increase at later time points." (PMID 22615852, 2012). "Recent findings further demonstrate a potential role for TXNIP in innate immunity via the NOD-like receptor-NLRP3/caspase-1 inflammasome activation and release of IL-1β in diabetes and oxidative stress." (PMID 22474421, 2012). "Retinal expression of IL-1β increased early after the induction of diabetes, continued to increase with progression of the disease, and was temporally associated with upregulation of markers of glial activation." (PMID 22615852, 2012). "In this study, we observed that the retinal expression of GFAP and acute-phase proteins increases in relation to diabetes duration with a pattern similar to that of IL-1β upregulation." (PMID 22615852, 2012). "Intercellular adhesion molecule-1, the transcription factors CEBP-β and -δ, and other IL-1β-dependent genes are upregulated in the diabetic retina." (PMID 22615852, 2012). "Interleukin-1 beta (IL-1β), interleukin 6 (IL-6), and C-reactive protein (CRP) are three inflammatory markers which have been shown to predict the development of diabetes, although this association is interpreted controversially." (PMID 23251619, 2012). "A recent trial of IL-1β blockade in people with type 2 diabetes showed improvements in glycemic control and pancreatic β-cell function, and additional studies to better define the potential role of IL-1β blockade in the treatment of diabetes are ongoing." (PMID 22348744, 2012). "IL-1β is increased in the retina in experimental diabetes, and such increase is due to increased retinal synthesis." (PMID 22615852, 2012). "RMD also inhibited diabetes-induced elevation in the levels of interleukin (IL)-1β, IL-6, interferon-γ and tumor necrosis factor-α." (PMID 21716679, 2011). "A reduction in functional β-cell mass leads to both major forms of diabetes; pro-inflammatory cytokines, such as interleukin-1beta (IL-1β) and gamma-interferon (γ-IFN), activate signaling pathways that direct pancreatic β-cell death and dysfunction." (PMID 21829464, 2011). "The cytokine levels of TNF-α, IL-1β, and IL-6 were increased in the patients with diabetes and diabetic rats." (PMID 21716679, 2011). "The effect of diabetes on the expression of various inflammatory (TNFα, IL-6, IL-1β and IFNγ) and apoptosis markers (caspase-1) was also evaluated in intact retinas from wt, ApoE−/−, TNFα−/− and ApoE−/−/TNFα−/− mice." (PMID 20856927, 2010). "In wt mice, diabetes resulted in a clear increase in TNFα, IL-6 and IL-1β mRNA expression levels (p<0.01, p<0.01 and p<0.05, respectively) and in a tendency to higher IFNγ and caspase-1 mRNA levels (n.s.)." (PMID 20856927, 2010). "In the retinas of diabetic wt mice, we also found significantly increased levels of TNFα, IL-6 and IL-1β mRNA expression and a tendency to increased IFNγ and caspase-1 mRNA, indicating some degree of local inflammation after 8 weeks of diabetes." (PMID 20856927, 2010). "Although the initial events leading to the development of diabetes are not well characterized, inflammatory cytokines, including interleukin-1β (IL-1β), appear to play an important role in both types of diabetes." (PMID 23554653, 2010). "The proinflammatory cytokine, IL-1β, plays a crucial role in negatively regulating β-cell function in type 2 diabetes mellitus." (PMID 23554653, 2010). "Interleukin-1β (IL-1β) plays an important role in the development of type 1 and type 2 diabetes mellitus." (PMID 23554653, 2010).
diabetes (continued). "As such, the balance between IL-1β and IL-1RA during an innate immune response plays a major role the pathogenesis of inflammatory diseases such as diabetes, arthritis, inflammatory bowel disease, and as presented here, TLR-mediated host defense mechanisms." (PMID 19503839, 2009). "Early in the course of diabetes mellitus (DM), mRNAs for IL-1β, TNF-α and other pro-inflammatory mediators are increased in the retina, partly from activated microglia." (PMID 19088876, 2008). "The results indicate that activation of caspase-1and subsequent production of IL-1β play an important role in the development of diabetes-induced retinal pathology." (PMID 18274606, 2007). "Our data demonstrate that curcumin, a compound with both anti-inflammatory and antioxidant properties, prevents diabetes-induced increase in IL-1β." (PMID 17437639, 2007). "In all stages of diabetes higher levels of IL-1β andTNF-α and lower levels of IL-2 and IL-6 were detected." (PMID 16864906, 2006). "Persistence ofsignificant difference between the cases with IDDM monitored for along time and controls in terms of IL-1β, IL-2, IL-6, andTNF-α supports continuous activation during the latestages of diabetes." (PMID 16864906, 2006). "Nanoflowers demonstrate rapid wound healing due to reduced inflammation, tissue regeneration, and angiogenesis in the diabetes-induced wound model by modulating tumor necrosis factor-α, CD-44, Ki-67, collagen deposition, ROS, interleukin-1β (IL-1β), IL-8, and IL-6 expression." (PMID 41737838, 2026). "TNF-α, IL-1β, IL-6, NF-κB and IL-17A are multifunctional cytokines, that are mainly related to immune regulation, and play a crucial role in the occurrence and progression of diabetes." (PMID 40046742, 2025). "Additionally, BCS directly suppressed the expression of genes associated with apoptosis (caspase-3), fibrosis (TGF-β1), and inflammation (IL-1β), further demonstrating its potential to mitigate diabetes-induced tissue damage and promote repair processes." (PMID 40002361, 2025). "In HCECs under hyperglycemic conditions, there was a 1.5-fold increase in IL-1β expression, suggesting that the increase in IL-1β levels observed in diabetes could be at least partially due to hyperglycemia." (PMID 41369370, 2025). "In addition, IL1B promotes the decline of pancreatic beta cell function during the aging process ultimately leading to diabetes." (PMID 40149697, 2025). "Diabetes also increased IL-1β and CCL2 in the kidneys, which was suppressed by VP3.15 treatment." (PMID 39880090, 2025). "Interestingly, PDB and flavone treatment significantly inhibited diabetes-mediated increase in levels of IL-1β, IFN-γ, TNF-a, and IL-6." (PMID 40486272, 2025). "Additionally, it has been reported that Myrt administration reduces elevated levels of NF‐κB, TNF‐α, and IL‐1β in liver and pancreatic tissues in a rat model of Type 2 Diabetes Mellitus." (PMID 40025781, 2025). "Beyond glycemic regulation, IL-1β contributes to the pathogenesis of diabetes complications." (PMID 40804870, 2025). "Future studies employing mast cell-deficient animal models or mast cell depletion strategies (such as knockout mice or targeted pharmacological depletion) will be crucial to definitively establish the extent to which mast cells drive IL-1β production and impair healing in diabetes." (PMID 40643520, 2025). "Furthermore, IL-1β and IL-8 were recently reported to be elevated together in the vitreous fluid of patients with diabetes and proliferative retinopathy." (PMID 38088456, 2024). "IL‐1β level was statistically significantly higher in diabetes and diabetes +2 mg/kg bW stevia groups compared to control, 2 mg/kg bW stevia, 25 mg/kg bW stevia, and diabetes +25 mg/kg bW stevia groups." (PMID 39479688, 2024). "Resveratrol may be used as a biotherapeutic agent, which significantly reduces diabetes-induced histone H4 and interleukin-1 beta-mediated liver and other target organ damage." (PMID 39128051, 2024).
diabetes (continued). "IL-1β is one of the most central players in the pathogenesis of diabetes." (PMID 39518962, 2024). "This could explain the long duration of diabetes required for caspase-1 activity to become dependent on IL-1β feedback in vivo." (PMID 39483336, 2024). "Conversely in subjects with low-apoB, LDL/ATP-induced WAT IL-1β-secretion was associated in the direction of lower diabetes risk, associating positively with IS and negatively with WAT expression of ADGRE1 and MCP1." (PMID 39511203, 2024). "Although chronic elevated IL-1β levels contribute to islet inflammation and β-cell apoptosis, and islet expression of IL-1β correlates with diabetes development, short-term production of small amounts of IL-1β by peritoneal macrophages also contributes to enhanced postprandial insulin secretion." (PMID 38346191, 2024). "In addition, we did not observe any elevation in cytokines associated with both an immune response and the development of diabetes (IL-1β, IL-6, IL-8, and TNFα) using ddPCR." (PMID 38400070, 2024). "We found that the two types of diabetes differed significantly in IL-1β expression." (PMID 38590527, 2024). "Liraglutide decreased expression of NLRP3, IL-18, and IL-1β pigs and mice with diabetes." (PMID 41424495, 2024). "The search strategy used for Google Scholar was ‘diabetes AND canakinumab, diabetes OR hyperglycemia OR prediabetes OR insulin resistance OR glucose intolerance AND canakinumab OR interleukin-1 beta antagonist’ with ‘all in title, with at least one of the words, 2013-2023’ filters applied." (PMID 39286685, 2024). "In conclusion, resveratrol can be used as an important biotherapeutic agent that significantly reduces histone and IL-1β-mediated cell damage due to diabetes, supports anti-inflammatory and innate host defense via β-defensin 1, and reduces target organ damage in organs such as liver and kidney." (PMID 39128051, 2024). "Here, we found that intravitreal injecting porous Se@SiO2 nanospheres could significantly suppress the expression of TNF-α, IFN-γ, and IL-1β in the retina, which was increased by diabetes." (PMID 38321393, 2024). "The model to predict SF-12 physical at 6-months had an R2 = 0.31 and included IL-1β as a significant predictor (p = 0.00), IL-18 (p = 0.05), the interaction of obese BMI and IL-1β (p = 0.04), and diabetes (p = 0.02), and reporting comorbid diabetes worsened SF-12 physical score at 6-months." (PMID 38702410, 2024). "In addition, treadmill exercise was activated in the PI3K/Akt/mTOR and AMPK/Sirt1 signaling pathways, while inhibiting the NF-kB/NLRP3/IL-1β signaling pathway in the hippocampus of rats with streptozotocin-induced type 2 diabetes mellitus." (PMID 38474387, 2024). "Elevated levels of IL-1β in diabetes activate the expression of other inflammatory cytokines and amplify the pro-inflammatory milieu, temporarily increase insulin secretion, which may be detrimental to metabolism." (PMID 38920850, 2024). "Liraglutide decreased expression of NLRP3, IL-18, and IL-1β in mice and pigs with diabetes." (PMID 41424495, 2024). "Similarly, agmatine was able to reduce TNF-α, IL-1β, IL-6, and IL-10 protein levels in the prefrontal cortex and hippocampus of mice with streptozotocin-induced diabetes." (PMID 38474387, 2024). "To further examine whether neutrophils are also primed for inflammatory cytokine production during diabetes, we measured the protein levels of tumor necrosis factor-α, interleukin-8 (IL-8), and IL-1β in neutrophils." (PMID 38654733, 2024). "The regulation of IL-1β signalling is maintained in healthy individuals but appears to be elevated during chronic pro-inflammatory disease states, which makes this pathway a valuable therapeutic target in diabetes." (PMID 39518962, 2024). "In this work, we discovered that quercetin and kaempferol had antidiabetic effects via suppression of IL-1β, IL-6, and IKKβ, suggesting that they may be promising candidate for the treatment of diabetes." (PMID 36826001, 2023).